PCK1 (phosphoenolpyruvate carboxykinase 1)
Diseases named in the same sentence as PCK1 in open-access papers (continued):
Sharing a sentence is not in itself a finding about the gene and the disease.
Brain atrophy (2 papers, 2010 to 2017). Partial or complete wasting (loss) of brain tissue that was once present. "Our study provides suggestive evidence for greater brain atrophy in MS patients bearing the PCK1 allele associated with AD-susceptibility, yielding new insights into potentially shared neurodegenerative process between MS and late onset AD." (PMID 21152065, 2010). "PCK1 is also associated with brain atrophy in multiple sclerosis." (PMID 28837672, 2017). "Our principal finding is that among the 722 MS subjects with MRI data, those bearing the PCK1 allele associated with AD susceptibility may have greater or accelerated brain atrophy." (PMID 21152065, 2010). "For the primary analysis, we used an additive model to assess whether the following late onset AD-associated variants influence brain atrophy and cognitive dysfunction in MS patients: PICALM (rs3851179), CR1 (rs6656401), CLU (rs11136000), PCK1 (rs8192708), and ZNF224 (rs3746319)." (PMID 21152065, 2010). "Therefore, we cannot exclude the possibility that PCK1 may influence cognitive manifestations of brain atrophy in MS." (PMID 21152065, 2010). "Thus, our statistical power is limited in addressing this question, and we cannot yet distinguish whether the effect of the PCK1 locus is one of accelerated brain atrophy in the context of MS or whether PCK1 affects the maximal BPF attained in the course of brain development." (PMID 21152065, 2010). "Regardless of the mechanism by which PCK1 affects T2LV, this effect appears to partially mediate the effect of PCK1 on brain atrophy, but much of the effect appears to be mediated by other mechanisms." (PMID 21152065, 2010).
brain infarction (2 papers, 2010 to 2022). Tissue necrosis in any area of the brain, including the cerebral hemispheres, the cerebellum, and the brain stem. "PH reduced brain infarction, neurological deficits, protein levels of glycolytic enzymes (GLUT-1, GLUT-3, PFK and LDH), gluconeogenic enzymes (PCK1 and PCK2), NOX activity and its subunit gp91, ROS, apoptotic cell death, glucose, and lactate, while raising ATP levels." (PMID 35740974, 2022).
Cachexia (2 papers, 2022 to 2025). Severe weight loss, wasting of muscle, loss of appetite, and general debility related to a chronic disease. "Next, we hypothesized that the cachexia-related expression of Pck1 and Pdk3 in CACS KL mice is regulated through the same IL-6–JAK–STAT signalling mechanism." (PMID 40275022, 2025). "In addition, some studies have reported reduced or unchanged Pck1 expression in certain cancer cachexia mouse models." (PMID 40275022, 2025). "Furthermore, the PCK1 mRNA level was higher in the cachexia group than in the NC group, and the application of 2-DG reversed this change." (PMID 36230949, 2022). "Similarly, in mouse cancer cachexia models, we observe IL-6–JAK–STAT-signalling-mediated induction of Pck1 and Pdk3 expression in the liver." (PMID 40275022, 2025).
cervical cancer (2 papers, 2023 to 2024). A primary or metastatic malignant neoplasm involving the cervix. "We employed the cervical cancer cell lines HCC94 and CaSki by manipulating the expression of key enzymes PCK1, PYGL, and GYS1, which are involved in glycogen metabolism, through siRNA transfection." (PMID 38871968, 2024). "The results revealed that PCK1, MT1A, AL096855.1, AC096711.2, FAR2P2, and AC099568.2 not only play a key role in the PPAR signaling pathway but also show good predictive value in cervical cancer patients." (PMID 37292383, 2023).
esophageal squamous cell carcinoma (2 papers, 2022 to 2024). Esophageal squamous cell carcinoma (ESCC) is a type of esophageal carcinoma (EC) that can affect any part of the esophagus, but is usually located in the upper or middle third. "AKT activation depends on the activation of SREBP1 by the PCK1 protein kinase to mediate the tumor lymph node and metastasis of esophageal squamous cell carcinoma." (PMID 39578429, 2024). "as report goes that the expression levels of AKT pS473, AKT-regulated PCK1 pS90, and nuclear SREBP1 were higher in esophageal squamous cell carcinoma specimens than in adjacent nontumor tissues." (PMID 39578429, 2024).
fibrosis (2 papers, 2021). the formation of excess fibrous connective tissue in an organ or tissue in a reparative or reactive process. "Recent studies have found that the transcription level of Pck1 is downregulated in the acute renal injury stage of FA-induced fibrosis, suggesting that this participates in mitochondrial energy metabolism, and promotes the progression of renal interstitial fibrosis." (PMID 33777519, 2021).
glucose metabolism disorder (2 papers, 2013 to 2021). "Subsequently, excessive iron led to oxidative stress and impaired mitochondrial function that further led to glucose metabolism disorder and reduced ATP production by regulating the expression of key enzyme genes or proteins including G6Pase, Pck1, and Cs." (PMID 34547719, 2021).
hepatic (2 papers, 2023 to 2026). "Male mice with liver Pck1 deficiency fed a normal diet displayed hepatic lipid disorder and liver injury, whereas fibrosis and inflammation were aggravated in mice fed a high-fat diet with drinking water containing fructose and glucose (HFCD-HF/G)." (PMID 36918564, 2023). "Mice lacking PCK1 in the liver can develop hepatitis and fibrosis, resulting in a fatty liver phenotype and liver damage." (PMID 41546098, 2026).
hepatitis C infection (2 papers, 2013 to 2017). "Both the transcription and translation of PCK1 have been reported to be up-regulated by hepatitis C virus infection, which clearly indicates its impact on hepatic glycolysis." (PMID 28112229, 2017). "In this study, the expression of PCK1 was significantly up-regulated in the virus infected group, which agrees with the results of previous studies in hepatitis C infection." (PMID 23923051, 2013).
Hypercortisolemia (2 papers, 2018 to 2022). "Hypercortisolemia increased blood glucose levels, and this corresponded with an increased transcript abundance of liver pck1, supporting GR activation of gluconeogenesis." (PMID 36127383, 2022).
lung adenocarcinoma (2 papers, 2023 to 2025). A carcinoma that arises from the lung and is characterized by the presence of malignant glandular epithelial cells. "The mRNA expression of PCK1 in lung adenocarcinoma cell lines appeared largely correlated with the expression of MLK4." (PMID 37407566, 2023). "These in vivo observations reinforced the in vitro findings that MLK4 mediated PCK1 transcription through CREB phosphorylation in lung adenocarcinoma." (PMID 37407566, 2023). "When PCK1 was knocked down in lung adenocarcinoma cell lines, a rescue by MLK4 overexpression led to an increase in PCK1 protein expression when compared to PCK1-knockdown cells." (PMID 37407566, 2023). "By siRNA-mediated CREB inhibition and selective pharmacologic inhibitor of CREB, we demonstrated that this regulation of PCK1 by CREB was also present in lung adenocarcinoma." (PMID 37407566, 2023). "Taken together, these findings demonstrated that PCK1 exerts an oncogenic effect in lung adenocarcinoma." (PMID 37407566, 2023). "Immunohistochemical studies on lung adenocarcinoma tissue microarray demonstrated that patients with high PCK1 expression had a worse prognosis, compatible to the findings in literature." (PMID 37407566, 2023). "We further demonstrated that PCK1 is an oncogenic factor in lung adenocarcinoma." (PMID 37407566, 2023). "To evaluate whether the survival difference for lung adenocarcinoma patients with high PCK1 level could be accounted for by using in vitro model, we performed knockdown of PCK1 in patient-derived organoids, which also led to suppression of organoid growth." (PMID 37407566, 2023). "Clinically, a high expression of PCK1 portended a poorer survival in lung adenocarcinoma." (PMID 37407566, 2023). "Together with the findings that KLF5, MLK4, and PCK1 appeared to be correlated in their expressions and predict a worse prognosis in lung adenocarcinoma, the study proposed a model of KLF5-MLK4-PCK1 signaling cascade that promotes glucose metabolism and tumorigenesis." (PMID 37407566, 2023). "Although PCK2 also appeared to have an oncogenic function in-vitro, we decided to focus on PCK1 because it was enriched by TCGA geneset analysis and had prognostic significance in lung adenocarcinoma, while PCK2 did not." (PMID 37407566, 2023).
metastatic disease (2 papers, 2019 to 2025). "Such a mechanism may also play a role in the survival of CRC cells during metastasis, as pyrimidine biosynthesis driven by phosphoenolpyruvate carboxykinase 1 (PCK1) was significantly upregulated in the mCRC liver colonization model using patient-derived metastatic tumor xenografts." (PMID 40442064, 2025).
pancreatic ductal adenocarcinoma (2 papers, 2021). An infiltrating adenocarcinoma that arises from the epithelial cells of the pancreas. "We found that most PCK1 mutations occur in pancreatic ductal adenocarcinoma (several samples with unknown histology subtype)." (PMID 34801052, 2021). "First The Cancer Genome Atlas (TCGA) cohort was consulted to examine PCK1 expression in pancreatic ductal adenocarcinoma (PDAC)." (PMID 34620839, 2021).
prostate carcinoma (2 papers, 2023 to 2024). A carcinoma that arises from epithelial cells of the prostate gland. "Importantly, two clinically used compounds (nilotinib and lapatinib) target PCK1 and cause AR-negative and NE-like PCa(prostate cancer) death." (PMID 39578429, 2024). "Therefore, targeting PCK1 reduces the neuroendocrine phenotype of prostate cancer cells and inhibits their growth." (PMID 39578429, 2024). "LIF/ZBTB46 axis is a key mechanism for PCK1-driven glucose metabolism, which may bring improvements in prostate cancer treatment after androgen deprivation therapy using PCK1 inhibitors." (PMID 37250903, 2023).
prostate tumors (2 papers, 2022 to 2023). "PCK1 could enhance prostate tumor cell proliferation and reciprocally elevates ZBTB46 levels to upregulate the expression of neuroendocrine markers." (PMID 37250903, 2023). "Intriguingly, targeting PCK1 has been found to attenuate the neuroendocrine phenotype of CRPC and impair the growth of these prostate tumors." (PMID 37250903, 2023). "Of the two other genes indicated as direct, downregulated targets for miR-32, namely Pck1 and Pdk4, Pck1 is not expressed in prostate tumors of patients (data not shown) and thus it is also unlikely to represent a clinically relevant miR-32 target in PC." (PMID 35228520, 2022). "Additionally, elevated PCK1 levels are correlated with prostate tumor progression by normal prostate-derived stromal cells." (PMID 37250903, 2023).
renal carcinoma (2 papers, 2023 to 2024). A carcinoma arising from the epithelium of the renal parenchyma or the renal pelvis. "Among them, the PCK1 gene was involved in lipid and amino acid metabolism, indicating its potential importance in the metabolic regulation of renal cancer patients." (PMID 37298343, 2023). "At present, studies on PCK1 in renal cancer are scarce, but the impact is large, suggesting that glucose metabolic reprogramming may be an effective target for renal cancer treatment." (PMID 39578429, 2024).
renal failure (2 papers, 2020 to 2025). "The expression of Pck1 is significantly reduced in mice with folate-induced renal interstitial fibrosis and is closely related to renal failure and ECM deposition." (PMID 39931687, 2025).
Sepsis (2 papers, 2018 to 2023). Sepsis is defined as life-threatening organ dysfunction caused by a dysregulated host response to infection. "Notably, these DEPs including Fads2, Fgb, Cypla2, Cyp2e1, Cfb, Serping1, Fgg, Etnppl, Agt, Hsd3b5, Gnmt, A2m, Pck1, Stat3, Ptpn1, Scd1, Slc2a1, and Uox were key genes in liver sepsis, which maybe associated with inflammation in sepsis." (PMID 37255592, 2023). "mRNA expression of Pck1 and G6pc further confirmed that hepatic GNG was inhibited in sepsis rats, which was partly restored by insulin treatment though the change of Pck1 was not significant." (PMID 29285858, 2018).
adenoma (1 paper, 2023). A neoplasm arising from the epithelium. "Next, we tested the expression levels of PCK1 in 491 pairs of CRC and corresponding normal epithelium tissues, as well as 4 adenoma tissue samples, using an IHC assay." (PMID 37062825, 2023).
atrial fibrillation (1 paper, 2024). A disorder characterized by an electrocardiographic finding of a supraventricular arrhythmia characterized by the replacement of consistent P waves by rapid oscillations or fibrillatory waves that vary in size, shape and timing and are accompanied by an irregular ventricular response. "Studies suggest that Pck1 is a key gene involved in the mechanisms of curcumin’s effects on atrial fibrillation." (PMID 39004726, 2024).
breast tumor (1 paper, 2024). "SHC2, LPL, PCK1, and KRT6B were all under-expressed, and only SFRP2 was highly expressed in the breast tumor." (PMID 38791477, 2024).
cardiac hypertrophy (1 paper, 2025). "PCK1 participates in myocardial glucose homeostasis by modulating both glycolysis and gluconeogenesis, and its dysregulation contributes to the development of cardiac hypertrophy." (PMID 40301189, 2025).
cognitive decline (1 paper, 2010). "Similarly, for PCK1, the minor allele, rs8192708G, significantly protected against cognitive decline in our cohort but was in fact the AD risk allele in the original GWA study." (PMID 20574532, 2010). "Indeed, in the case of PCK1, two prior replication studies found evidence that the major allele, rs8192708A, may increase risk for dementia, consistent with our results suggesting an association between this allele and both cognitive decline and AD." (PMID 20574532, 2010). "Our finding that the PCK1 association with cognitive decline is not explained by AD pathology, Lewy bodies, or infarcts suggests that this locus might influence additional, unmeasured pathologies." (PMID 20574532, 2010). "Finally, in a series of statistical mediation analyses, we tested hypotheses about the causal chain of events linking genetic variation in the ZNF224 and PCK1 loci with cognitive decline, with strikingly different outcomes." (PMID 20574532, 2010).
Cognitive impairment (1 paper, 2010). Abnormal cognition is characterized by deficits in thinking, reasoning, or remembering. "In contrast, the PCK1 SNP (rs8192708) was significantly associated with global cognition (p = 3.57×10−4) but not global AD pathology (p = 0.056), suggesting that this locus may influence cognitive impairment through mechanisms other than AD pathology." (PMID 20574532, 2010). "Episodic memory impairment, the most characteristic cognitive deficit of AD, was associated with both the ZNF224 locus (p = 0.003) and the PCK1 locus (p = 3.69×10−4)." (PMID 20574532, 2010). "The association of ZNF224 with cognitive impairment was mediated by neurofibrillary tangles, whereas PCK1 largely influenced cognition independent of AD pathology, as well as Lewy bodies and infarcts." (PMID 20574532, 2010).
colon adenocarcinoma (1 paper, 2022). "Results showed correlations of PCK1 with a cluster of differentiation 4-positive (CD4+) T cells and macrophages, while neutrophils were negatively correlated in colon adenocarcinoma (COAD) and rectal adenocarcinoma (READ) patients." (PMID 36193307, 2022).
colorectal tumor (1 paper, 2023). "PCK1 also contributes to liver metastatic colonization of colorectal tumor by increasing pyrimidine nucleotide biosynthesis under hypoxia." (PMID 37250903, 2023). "Pharmacologic inhibition of PCK1 could blocked the liver metastatic colonization of colorectal tumors." (PMID 37250903, 2023).
Crohn disease (1 paper, 2025). A gastrointestinal disorder characterized by chronic inflammation involving all layers of the intestinal wall, noncaseating granulomas affecting the intestinal wall and regional lymph nodes, and transmural fibrosis. "Furthermore, scratch assays demonstrated that Si-PCK1 inhibited the migration of RA-FLS, while flow cytometry analyses indicated that Si-PCK1 promoted apoptosis in RA-FLS, consistent with previous reports on PCK1 knockout in Crohn’s disease." (PMID 40755786, 2025).
dementia (1 paper, 2010). Loss of intellectual abilities interfering with an individual's social and occupational functions. "Again, the association between PCK1 and global cognition remained significant (Beta = 0.39, p = 2.04×10−4), and PCK1 continued to explain 3% of the residual variance in global cognition in our cohort after adjusting for the three most common brain pathologies associated with dementia." (PMID 20574532, 2010). "In contrast, similar to nearly all AD GWA studies performed to date, the initial reports of association with the PCK1 and ZNF224 loci come from AD cases recruited from a neurology clinic population with prevalent dementia." (PMID 20574532, 2010). "In contrast, we find that the association between PCK1 and cognition is largely independent of not only AD pathology, but also Lewy bodies, and infarcts, which together comprise the three most common known brain pathologies associated with dementia." (PMID 20574532, 2010).
diabetic nephropathy (1 paper, 2025). "Recent studies have highlighted the significant role of PCK1 in the progression of diabetic nephropathy and acute tubular injury." (PMID 40442892, 2025).
diabetic neuropathy (1 paper, 2020). A chronic, pathological complication associated with diabetes mellitus, where nerve damages are incurred due to diabetic microvascular injury involving small blood vessels that supply these nerves, resulting in peripheral and/or autonomic nerve dysfunction. "PCK1 may also participate in the progression of diabetic neuropathy." (PMID 32337289, 2020).
dilated cardiomyopathy (1 paper, 2013). Cardiomyopathy which is characterized by dilation and contractile dysfunction of the left and right ventricles. "Among the remaining 19 DEGs, IGF1 (NO.17), MYL2 (No. 31), PCK1 (No. 33) and PRKACA (No. 39) were involved in the pmAF – related PPAR signaling pathways, focal adhesion and dilated cardiomyopathy." (PMID 24204599, 2013).
Dravet syndrome (1 paper, 2021). "This study builds on our previous work that demonstrated metabolic deficits and down-regulation of key gluconeogenic genes, pck1 and pck2 in scn1lab mutants, a translatable zebrafish model of Dravet syndrome." (PMID 33842883, 2021). "We utilized a translatable zebrafish model of Dravet syndrome (scn1lab) which exhibits key characteristics of patients with Dravet syndrome and shows metabolic deficits accompanied by down-regulation of gluconeogenesis genes, pck1 and pck2." (PMID 33842883, 2021). "Predictably, oxaloacetate, which is known to increase flux through PEPCK and stiripentol, an antiepileptic drug used in Dravet syndrome patients did not up-regulate either pck1 or pck2." (PMID 33842883, 2021).
E. coli infection (1 paper, 2018). "The enhanced expression of Pck1 suggests that both Mkp-1 knockout and E. coli infection stimulate gluconeogenesis." (PMID 30563203, 2018). "E. coli infection further enhanced the expression of Pck1 protein in both Mkp-1+/+ and Mkp-1−/− mice." (PMID 30563203, 2018). "Our RNA-seq analysis indicates that liver Pck1 mRNA levels were significantly increased in both Mkp-1+/+ and Mkp-1−/− mice following E. coli infection." (PMID 30563203, 2018). "The dramatically enhanced Pck1 expression suggests that in the absence of Mkp-1 animals adapt a more active ‘wasting’ program to meet their metabolic needs, partially explaining how Mkp-1−/− mice utilize less glycogen following E. coli infection." (PMID 30563203, 2018).
endocarditis (1 paper, 2017). Inflammation of the endocardium. "Genes expressed significantly lower in epididymal adipose tissue obtained from rats with endocarditis were the genes for the adiponectin receptor type 1 (AdipoR1) and phosphoenolpyruvate carboxykinase-1 (PEPCK-1)." (PMID 28428684, 2017).